LEP (leptin)
Diseases named in the same sentence as LEP in open-access papers (continued):
Sharing a sentence is not in itself a finding about the gene and the disease.
coronary artery disease (99 papers, 2009 to 2026). "Background/Objectives: The study aimed to examine the association between the total SPPB score and serum leptin levels in patients with coronary artery disease (CAD) undergoing elective percutaneous coronary intervention (PCI)." (PMID 41594231, 2026). "Elevated leptin has been associated with atherosclerosis and identified as an independent associated factor of coronary artery disease (CAD)." (PMID 41470134, 2025). "Despite the inverse correlation with NT-proBNP, an increase in leptin is described to be associated with higher mortality, hospitalization rate, or fatal vascular events in coronary artery disease and with the progression of heart failure." (PMID 37176525, 2023). "A previous study observed that diets rich in sugar can lead to abnormalities associated with increased coronary heart disease, including leptin resistance, high levels of glucose, insulin, and uric acid." (PMID 38140309, 2023). "A study regarding the prevention of coronary diseases in Scotland (WOSCOPS) showed a moderate increase in a leptin associated risk of developing CAD." (PMID 33735200, 2021). "This is in line with the idea that leptin resistance, an insensitivity to feedback signaling of adipose stores to the CNS, is linked with increased risk for ischemic heart disease in patients." (PMID 25994184, 2015). "This prospective observational data support the use of serum leptin for estimation of risk for ischemic heart disease independently of traditional risk factors." (PMID 25994184, 2015). "Leptin concentrations were independently associated with coronary heart disease and predicted CV events in subjects with coronary atherosclerosis." (PMID 24245495, 2013). "Associationsa of adiponectin and leptin with incident coronary heart disease and stroke in the Jackson Heart Study (N = 4,571)." (PMID 24350185, 2013). "Leptin, BMI, and history of coronary artery disease were found to be associated with visual-analog-scale scores for chronic hand pain (R2 = 0.36 unadjusted analysis, p-values≤0.04)." (PMID 23110114, 2012). "Leptin serum concentration, BMI, and coronary artery disease were associated with the intensity of chronic hand OA pain." (PMID 23110114, 2012). "Our study found leptin, BMI, and history of coronary artery disease were associated with chronic pain intensity of hand OA." (PMID 23110114, 2012). "In multivariable analyses, leptin serum concentration, BMI, and history of coronary artery disease were associated with hand pain (R2 = 0.36, all p-values<0.05)." (PMID 23110114, 2012). "Furthermore, raised leptin levels were associated with a lower incidence of adverse events, morbidity, and mortality in coronary heart-disease patients." (PMID 37238961, 2023). "A 2017 meta-analysis that included 13 case-control and cohort studies concluded that while high leptin levels were associated with coronary heart disease mortality in simple models, further adjustment for other established heart disease risk factors resulted in the loss of statistical significance." (PMID 36771486, 2023). "For example, we found evidence of two statements that ‘Leptin PREDISPOSES Coronary heart disease’." (PMID 33165574, 2021). "We found that high levels of leptin were related to increased risks of ischemic heart disease independently of traditional risk factors in men and that this prognostic information also remained significant when carotid IMT and aortic PWV were both included in the Cox regression." (PMID 25994184, 2015). "Leptin, an adipocyte-derived hormone, plays an important role in metabolism, adiposity, and vascular inflammation, and has been implicated in the development of coronary heart disease." (PMID 24223557, 2013). "However, BMI, leptin serum concentration, and history of coronary artery disease were associated with chronic hand OA pain." (PMID 23110114, 2012).
coronary artery disease (continued). "Furthermore, a recent study shows that low serum leptin levels are associated with increased cardiovascular events and mortality in patients with stable coronary artery disease." (PMID 23270329, 2012). "Given the inconsistencies in the available data, we sought to assess the association between the total SPPB score and serum leptin levels in patients with coronary artery disease (CAD) before elective percutaneous coronary intervention (PCI)." (PMID 41594231, 2026). "Leptin levels and computed tomography-based measures of body composition and coronary heart disease among patients with metastatic castration-resistant prostate cancer." (PMID 39557398, 2025). "In summary, the combined treatment of Du Meridian moxibustion and ear acupuncture for insomnia in patients with coronary heart disease can regulate the expression of serum melatonin, leptin, and neurotransmitters." (PMID 39183410, 2024). "The combination of Du Meridian acupuncture with ear acupuncture in the treatment of insomnia in coronary heart disease can regulate the expression of serum melatonin, leptin, and neurotransmitters, alleviate symptoms, and improve therapeutic efficacy." (PMID 39183410, 2024). "Different studies have also reported that higher levels of leptin correlate with an increased number of stenotic coronary arteries and arterial stiffness in patients with coronary heart disease." (PMID 38397015, 2024). "Leptin is implicated in CVD events, and hyperleptinemia has been linked to the presence and severity of coronary heart disease (CHD) and HF." (PMID 38397015, 2024). "Resistin also acts unfavorably and promotes the progression of coronary artery disease by mechanisms similar to those of leptin, namely by reducing endothelial NO production and increasing ROS." (PMID 33660958, 2021). "Leptin loses its ability to carry out its physiological function at high serum levels, and many studies have associated this loss of function with the development of coronary artery disease (CAD)." (PMID 34178553, 2021). "As a conclusion, the effects of serum level of leptin or adiponectin were higher among CAD patients than healthy individuals and associated with the extent of coronary artery disease and our findings were in consistence with other previously reports." (PMID 33148166, 2020). "In another cohort of patients with coronary artery disease, increased leptin concentration was a predictor of cardiovascular mortality and nonfatal acute myocardial infarction (MI) in women (HR = 1.28; 95% CI = 1.01–1.62; p = 0.04), but not in men." (PMID 31940832, 2020). "This study aimed to determine the relationship between leptin/adiponectin (L/A) ratio and the extent and severity of coronary artery disease (CAD)." (PMID 33148166, 2020). "In the current study, serum levels of leptin were associated with incident of CAD and it was also directly related to the extent of coronary artery disease." (PMID 33148166, 2020). "The aim of this study was to investigate the relationship between the leptin and L/A ratio indices and the severity and extent of coronary artery disease using angiography and GS." (PMID 33148166, 2020). "The current study investigated any relationship between the leptin, adiponectin and L/A ratio and the extent or severity of coronary artery disease based on the number of involved vessels and GS, and this was the first study in this field." (PMID 33148166, 2020). "Genetic evidence from different human populations has implicatedLEP/LEPR in the pathogenesis of coronary artery disease (CAD), and suggeststhat certain LEP/LEPR gene polymorphisms may increase the risk of CAD." (PMID 32049202, 2020). "We used samples obtained from the right atrium, which usually remains well protected against systematic CVD such as coronary artery diseases and arterial hypertension, and treated them in an in vitro model with a supraphysiological dosage of leptin." (PMID 31019683, 2019).
coronary artery disease (continued). "Our aim was to investigate the relationship of leptin and the surrogate marker carotid-femoral pulse wave velocity (cfPWV) in coronary artery disease (CAD) patients." (PMID 27151106, 2016). "In summary we found that levels of leptin were positively related to the hazard ratio (HR) of ischemic heart disease in both men and women and this was independently of age, HbA1c, BMI, systolic blood pressure and LDL-cholesterol/HDL-cholesterol ratio." (PMID 25994184, 2015). "Subjects with MetS or coronary heart disease have been reported to have higher leptin expression in EAT." (PMID 25383099, 2014). "Endothelium-independent vasodilation by leptin was also identified in the saphenous vein and internal mammary artery ex vivo in humans with coronary artery disease." (PMID 24410779, 2014). "In fact, it has been shown that leptin expression was higher in EAT obtained from subjects with MetS or coronary heart disease." (PMID 25383099, 2014). "In one study that examined patients with coronary heart disease, simvastatin treatment resulted in a significant decrease in blood leptin." (PMID 24255692, 2013). "Body weight, serum triglyceride concentration and systolic blood pressure were all significantly related to the logarithm of the serum leptin concentration in stable coronary artery disease patients." (PMID 22642879, 2012). "Leptin concentrations were significantly higher in diabetic and coronary artery disease patients than in controls." (PMID 22642879, 2012). "The aim of this study was to determine the relationship of leptin and adiponectin with coronary artery diseases." (PMID 22577414, 2010). "The objective of this study was to determine the relationship between the serum level of leptin and adiponectin in patients with ischemic heart diseases, as well as evaluation of the relationship between serum lipids and the two hormones." (PMID 22577414, 2010). "Various studies have demonstrated that high serum level of leptin and the incidence of coronary artery diseases are correlated." (PMID 22577414, 2010). "Leptin levels were analyzed as a log-transformed continuous variable, and multivariable Cox regression was used to assess associations with hard CVD events, including coronary heart disease and stroke." (PMID 39682585, 2024). "Leptin, an adipocyte-derived pro-inflammatory adipokine, contributes to the low-grade inflammatory state in overweight/obese individuals and is implicated in CVD events, with hyperleptinemia linked to coronary heart disease and heart failure." (PMID 39858399, 2024). "The researchers suggested that this paradox might be related to the elevation of leptin in patients with coronary heart disease and COPD." (PMID 37400821, 2023). "Serum levels of specific adipokines, including leptin, adiponectin, resistin, and retinol-binding protein 4 (RBP4), have been associated with the presence of coronary artery disease (CAD), suggesting a potential role of these adipokines in the pathogenesis of CAD." (PMID 36964443, 2023). "Regarding endothelium status, leptin has been pointed out as an important key factor in platelet activation processes in coronary heart-disease patients, as well as by its ability to enhance tissue factor expression and adhesion-molecules development, compromising endothelium functioning." (PMID 37238961, 2023). "In that same study, it has shown that leptin and resistin are linked with coronary artery disease regardless of CRP." (PMID 36299943, 2022). "Hyperleptinemia, on the other hand, as a consequence of leptin resistance in obesity and metabolic syndrome, decreases NO release and promotes reactive oxygen species (ROS) formation, which worsens the hypercoagulable state and coronary artery disease." (PMID 33660958, 2021). "Elevated leptin levels were associated with an increased risk of heart failure in men without pre-existing coronary heart disease, independent of BMI and potential mediators." (PMID 32655492, 2020).
coronary artery disease (continued). "Moreover, increased plasma leptin levels were positively correlated with the total number of stenotic coronary arteries in patients with coronary artery disease." (PMID 32655492, 2020). "Moreover, several clinical studies have shown that the plasma leptin level is an independent predictor of incident coronary artery disease." (PMID 24410779, 2014). "It has been shown that EAT produces inflammatory mediators such as interleukin (IL)-6, IL-1b, tumor necrosis factor (TNF)-a, and monocyte chemotactic protein (MCP-1) in patients with significant coronary artery disease and expresses mRNAs of adiponectin, resistin, leptin, IL-6, TNF-a, and CD-45." (PMID 23762053, 2013). "Studies on the role of serum leptin in coronary artery disease are scarce." (PMID 22642879, 2012). "The predictive power of leptin on cardiovascular disease was addressed in a report from the Quebec cardiovascular study, eighty-six patients who developed ischemic heart disease were compared with referent matched for a number of traditional cardiovascular risk factor including body mass index." (PMID 22642879, 2012). "The results of our study indicated that serum levels of leptin were significantly higher among CAD patients than in healthy control subjects and leptin was also directly related to the extent of coronary artery disease, based on number of involved vessels." (PMID 33148166, 2020). "For example, the increase in leptin level associated with being in a manual rather than a non-manual social class group (∼20%) would be associated with an increase in the relative risk of coronary heart disease of ∼1–2% at the individual level." (PMID 25437893, 2015). "Previous studies have found increased secretion of leptin and IL-6 and decreased secretion of cardioprotective lipocalin in EAT in patients with coronary artery disease, leading to immune cell activation and inflammatory responses." (PMID 36158806, 2022). "In a later study, increased waist circumference and augmented serum leptin levels occurred concomitant to elevated serum cholesterol, triglyceride and CRP expression in coronary artery disease (CAD) patients compared with healthy controls." (PMID 34064112, 2021). "Plasma levels of leptin, and adiponectin can indicate the extent of coronary artery diseases but leptin may be a better marker of extent of CAD than either L/A ratio or adiponectin separately." (PMID 33148166, 2020). "Recent studies of leptin production in patients without coronary artery disease have shown that LEP gene expression is higher in SAT than in visceral AT." (PMID 41226064, 2025). "Increased PWV had been shown to predict a greater risk of CV morbidity and mortality in hypertensive and diabetic patients, but the relationship of serum leptin and arterial stiffness in patients with coronary artery disease (CAD) is not clear." (PMID 27151106, 2016). "Leptin did not emerge as a predictor in coronary artery disease." (PMID 22642879, 2012). "Interestingly, a recent study has proposed leptin as a contributing factor for developing heart failure in obese men with no history of preexisting coronary heart disease but not in heart failure patients with coronary heart disease." (PMID 22848545, 2012).
hyperlipidemia (96 papers, 2005 to 2026). "Since HFD causes hyperlipidemia and cardiovascular disease, we analyzed the blood composition, including insulin and leptin levels and lipid profiles in HFD-fed obese mice." (PMID 36145056, 2022). "In summary, we clearly demonstrate that intrauterine exposure to hyperlipidemia is associated with elevated blood pressure in adulthood, which is related to sustained increase in serum leptin levels via epigenetic reprogramming of the leptin promoter." (PMID 33431976, 2021). "Psyllium husk ethanolic extract can reduce lipid peroxidation, increase CAT and GSH activities, and increase the hormones, leptin, and adiponectin associated with hyperlipidemia." (PMID 33923513, 2021). "Our findings provide new insights that maternal hyperlipidemia is associated with elevated blood pressure in offspring and is associated with increases in leptin levels through epigenetic memory." (PMID 33431976, 2021). "Overactivation of the sympathic system can be caused by increased plasma levels of leptin, secondary to leptin resistance in MetS, or by hyperlipidemia, particularly the high circulating levels of FFA." (PMID 26580647, 2015). "In leptin-deficient ob/ob mice, repeated intraperitoneal PP injection decreases body weight gain and improves insulin resistance and hyperlipidaemia." (PMID 22899902, 2012). "Subcutaneous administration of recombinant leptin reduces fat mass, hyperinsulinaemia, and hyperlipidaemia in obese children with congenital leptin deficiency." (PMID 22899902, 2012). "Thereafter, the leptin gene deficiency and severe hyperlipidemia might be responsible for the ineffectiveness of the long-term metformin treatment on fatty liver in Zucker rats." (PMID 31749893, 2019). "Thus, our results suggest that maternal hyperlipidemia during pregnancy might be associated with an elevation of blood pressure and chronically elevated leptin levels in offspring." (PMID 33431976, 2021). "In this study, we established a rat model of maternal hyperlipidemia and found that excessive intrauterine lipid exposure was associated with elevated blood pressure in offspring, which was associated with a sustained increase in serum leptin levels in offspring." (PMID 33431976, 2021). "TQ reduced body weight, body weight gain and adipocyte size, improved hyperlipidemia, and normalized the levels of leptin and adiponectin." (PMID 40542063, 2025). "The pathogenesis remains poorly understood, with some cases suggesting a link to hormone leptin dysregulation and/or hyperlipidemia." (PMID 39081442, 2024). "Studies have shown that YT extract has beneficial effects of alleviating hyperlipidemia by regulating leptin and adiponectin levels in the liver." (PMID 36742424, 2023). "Leptin and adiponectin are mainly secreted by adipose tissue and play an essential role in the development and progression of hyperlipidemia." (PMID 36742424, 2023). "After 24 weeks of HFD feeding, these mice developed increased body weight, excessive storage of white adipose tissue, hypercholesteremia, hyperlipidaemia and high plasma leptin levels." (PMID 35017550, 2022). "In the occurrence and development of hyperlipidemia, leptin production is negatively related to the level of triglycerides (TGs)." (PMID 36539694, 2022). "leaf (COE) in hyperlipidemia via the leptin/Janus kinase 2 (JAK2)/signal transducer and activator of transcription 3 (STAT3) pathway." (PMID 36539694, 2022). "Hyperlipidemia, impaired energy expenditure, insulin sensitivity, as well as higher plasma leptin are all shown in the FXN knock-in/knock-out (KIKO) mouse, which mimics T2D-like symptoms." (PMID 35677823, 2022). "The leptin/Janus kinase 2 (JAK2)/signal transducer and activator of transcription 3 (STAT3) pathway is significantly associated with the pathogenesis of hyperlipidemia via alterations in lipid metabolites." (PMID 36539694, 2022).